SFRP5 (secreted frizzled related protein 5)
Diseases named in the same sentence as SFRP5 in open-access papers (continued):
Sharing a sentence is not in itself a finding about the gene and the disease.
prostate carcinoma (1 paper, 2017). A carcinoma that arises from epithelial cells of the prostate gland. "Interestingly, in the two latter mentioned studies, DNA hypermethylation of SFRP2, SFRP3, and SFRP5 was detected in both cell lines and human prostate cancer tissues." (PMID 29079735, 2017).
renal carcinoma (1 paper, 2012). A carcinoma arising from the epithelium of the renal parenchyma or the renal pelvis. "The methylation levels of six Wnt antagonist genes (sFRP-1, sFRP-2, sFRP-4, sFRP-5, Wif-1, and Dkk-3) were significantly higher in renal cancer compared to normal renal tissues." (PMID 22325146, 2012). "sFRP-5 was epigenetically suppressed in RCC and its overexpression induced apoptosis in renal cancer cell lines." (PMID 22325146, 2012).
Sepsis (1 paper, 2023). Sepsis is defined as life-threatening organ dysfunction caused by a dysregulated host response to infection. "Therefore, we conducted a large clinical study focusing on the association between SFRP5 and organ dysfunction, regulation of SFRP5 in critical illness and sepsis as well as possible function as a prognostic biomarker." (PMID 36830849, 2023). "The dysregulation of the Wnt5a / SFRP5 system has already been demonstrated in a smaller study of 60 critically ill patients with sepsis." (PMID 36830849, 2023). "Firstly, the Wnt5a/SFRP5 system is not only dysregulated in sepsis alone, but also in critical illness in general." (PMID 36830849, 2023). "The aim of this study was to elucidate the role of SFRP5 in critical illness and sepsis and to determine its value as a prognostic biomarker for mortality." (PMID 36830849, 2023). "Thirdly, septic patients seem to restore levels of SFRP5 during sepsis, reflecting the later stages of anti-inflammation." (PMID 36830849, 2023). "This study points to the role of the anti-inflammatory mediator SFRP5 not only in sepsis but also in nonseptic critically ill patients and associates high levels of SFRP5 to worse outcomes, predominantly in nonseptic critically ill patients." (PMID 36830849, 2023). "Given the close links between metabolism and inflammation seen in the Wnt pathway, one might suspect that SFRP5 also plays a role in the dysregulated immune response in critical illness and sepsis." (PMID 36830849, 2023). "Furthermore, septic patients recovered levels of SFRP5 in the time course of sepsis." (PMID 36830849, 2023). "Aside from those studies, the role of SFRP5 in human sepsis remains unclear." (PMID 36830849, 2023). "In fact, in a small study with 60 critically ill patients, the authors showed a dysregulation of the Wnt5a/SFRP5 system in human sepsis but did not observe statistical alterations in SFRP5 concentrations." (PMID 36830849, 2023).
stable angina (1 paper, 2025). "The third key finding of this study is that the CC genotype carriers with both stable angina and ACS had significantly higher HbA1C, total WBC count, and lymphocyte count compared to those with the AA genotype, along with lower adiponectin and Sfrp5 levels." (PMID 40303486, 2025).
thymoma (1 paper, 2022). A neoplasm arising from the epithelial cells of the thymus. "SFRP2 and SFRP5 expression levels were increased in B2 thymomas, while AB thymomas showed increased DKK1 and DKK4 expression compared to other TETs and NTs." (PMID 35965500, 2022).
ulcerative colitis (1 paper, 2025). An inflammatory bowel disease involving the mucosal surface of the large intestine and rectum. "In this study, the methylation and expression status of SFRP2, SFRP4, SFRP5, APC1, and APC2 genes were evaluated for the first time in ulcerative colitis patients in the Turkish population." (PMID 40521787, 2025).
valvular heart disease (1 paper, 2022). "In this study, we present baseline plasma concentrations of WNT-5a, sFRP-1, sFRP-5, and WIF-1 in patients with coronary and/or valvular heart disease." (PMID 36440011, 2022).
vitiligo (1 paper, 2024). Generalized well circumscribed patches of leukoderma that are generally distributed over symmetric body locations and is due to autoimmune destruction of melanocytes. "SFRP5 is known to regulate the development of various tissues and organs, but its role in vitiligo, characterized by skin depigmentation, has been unclear due to its inhibition of Wnt signaling." (PMID 38920996, 2024). "SFRP5 inhibits melanin synthesis in melanocytes in vitiligo by suppressing the Wnt/β-catenin signaling pathway, and we expect that Sfrp5pepD will have the same effect." (PMID 38920996, 2024). "SFRP5 was overexpressed in the skin lesions of vitiligo patients." (PMID 38920996, 2024). "Overexpression of SFRP5 was found in vitiligo skin lesions compared to normal melanocytes." (PMID 38920996, 2024). "A recent study suggested that SFRP5 could affect melanogenesis in vitiligo by regulating Wnt signaling." (PMID 38920996, 2024). "Indeed, SFRP5 inhibits melanin synthesis in melanocytes in vitiligo by suppressing the Wnt/β-catenin signaling pathway." (PMID 38920996, 2024).
tumor (44 papers, 2006 to 2025). "Some studies have also suggested that SFRP5, as a physiological tumor suppressor, has potential diagnostic and prognostic value in CRC, although the specific mechanisms have not been clarified." (PMID 39729237, 2025). "A previous finding confirmed the role of SFRP5 as a physiologic tumor suppressor and demonstrated its potential diagnostic and prognostic value in CRC." (PMID 34205081, 2021). "Both SFRP1 and SFRP5 methylation were shown to occur frequently and be tumour specific with a strong association to poor clinical patient outcome." (PMID 18826564, 2008). "Activation of Wnt signaling, observed in tumor samples through the methylation of SFRP5 gene, could cause tumor resistance to EGFR TKIs and, on account of this it was associated with poorer treatment outcomes." (PMID 34885084, 2021). "Moreover, the abnormal expression of UHRF1 and SFRP5 is associated with tumor recurrence." (PMID 40301374, 2025). "Many studies have reported that SFRP5 is frequently silenced and correlated with promoter methylation in tumours and inflammation, and that demethylating drugs can reverse this silencing to restore SFRP5 expression." (PMID 40595027, 2025). "Gene expression of all three studied genes, PDE4B (p < 0.0001), PDE4D (p < 0.0001), and SFRP5 (p < 0.0001), was significantly lower in tumor tissue in comparison to the control tissue." (PMID 39202484, 2024). "In conclusion, our results emphasize the potential clinical utility of PDE4B, PDE4D, and SFRP5, genes that impact tumor initiation, progression, and metastasis, as biomarkers for CRC." (PMID 39202484, 2024). "Research indicates that in NSCLC cells resistant to EGFR-TKIs, diminished expression of SFRP5 triggers the activation of the Wnt pathway, facilitating tumor advancement and drug resistance via EMT and Akt2 signaling pathways mediated by TWIST." (PMID 39196297, 2024). "For the AC subtype, significantly higher concentrations of SFRP1 and SFRP5 in tumour samples compared to NT were detected (p = 0.022 and p = 0.011, respectively), while the level of SFRP2 protein was reduced in tumour samples (p < 0.001)." (PMID 37999144, 2023). "The aim of this study was to evaluate the concentrations of SFRP1, SFRP2, and SFRP5 proteins in tumour and non-tumour (NT) samples obtained from 65 patients with primary NSCLC." (PMID 37999144, 2023). "Higher SFRP5 protein concentrations were observed in tumour samples with stage III compared to stage I NSCLC (10,475.35 vs. 3789.88; p = 0.042)." (PMID 37999144, 2023). "In this study, in patients with adenocarcinoma, a significantly higher concentration of SFRP5 was observed in tumour than in NT samples." (PMID 37999144, 2023). "SFRP5 (secreted frizzled related protein 5) can negatively regulate the Wnt pathway, and is regarded as a tumor suppressor." (PMID 35252174, 2022). "A six-gene risk score, the SCCHN TMI (SCCHN-tumor matrisome index: composed of MASP1, EGFL6, SFRP5, SPP1, MMP8 and P4HA1) was constructed and used to stratify patients into risk groups." (PMID 34830910, 2021). "The plasma level of SFRP5 is significantly reduced in obese patients and SFRP5 expression is also decreased in various tumor tissues." (PMID 34350120, 2021). "Our gene regulation, DNA methylation, cell growth, and colony formation results indicate that SFRP2 and SFRP5 both act as tumour suppressors of MPM and are silenced by DNA hypermethylation." (PMID 29386699, 2017). "SFRP2 and SFRP5 tumour-suppressive activity in eleven MPM lines was confirmed, and long-term asbestos exposure led to reduced expression of the SFRP1 and SFRP2 genes in the mesothelium (MeT-5A) via epigenetic alterations." (PMID 29386699, 2017). "In the BMI1 over-expressing cells, DNA methylation increased in the WNT antagonist gene, SFRP5 (Secreted frizzled-related protein 5), as the culture passages increased, perhaps modelling similar hypermethylation of this gene that has been catalogued among human tumours." (PMID 28587163, 2017).
tumor (continued). "Our manuscript mainly discussed the average methylation rate of SFRPs (SFRP1, SFRP2, SFRP4, and SFRP5) promoters are significantly high in tumor tissue samples and the average CpG island methylation rate among different pathological levels of cutaneous SCC between these genes are different." (PMID 26394929, 2015). "Patched Homolog 1 (PTCH1) is the SHH receptor and is the most commonly mutated tumor suppressor in BCC, whereas adenomatous polyposis coli (APC), secreted frizzled-related protein 1 (SFRP1), SFRP2, SFRP4, and SFRP5 are all negative regulators of the canonical WNT pathway." (PMID 23284750, 2012). "It is tempting to speculate that increased silencing of putative tumor suppressors correlates with increasingly invasive behavior, a notion that is supported by our finding of differential SFRP5 methylation in iBCC versus nBCC and sBCC." (PMID 23284750, 2012). "Wnt signaling pathway proteins, particularly SFRP1 and SFRP5, are crucial as their reduced levels due to promoter methylation lead to cytoplasmic and nuclear accumulation of β-catenin, facilitating tumor progression; thereby, these proteins may serve as biomarkers for malignant progression." (PMID 40565504, 2025). "Likewise, we observed a higher concentration in AC tumour samples compared to NT samples, and also could suggest the oncogenic role of SFRP5 in adenocarcinoma." (PMID 37999144, 2023). "Interestingly, it was observed that, in the total NSCLC group, an increased level of SFRP5 was present in tumour samples obtained from stage III NSCLC patients compared to stage I. In the literature, the SFRP5 protein concentration in cancers is still not explored enough." (PMID 37999144, 2023). "In addition, we analyzed the gene expression profile of GSE85841 that included eight LUAD samples and adjacent non-tumor samples with adjusted P < 0.05 and logFC≥1.5, and researched the top five most significantly upregulated genes: SFRP5, CST2, SPP1, GCNT3, and NHLRC1." (PMID 35399076, 2022). "Increased concentrations of SFRP1 and SFRP5 were present in stage III NSCLC samples, while the tumour samples with high pleural invasion (PL2) had an increased level of SFRP2." (PMID 37999144, 2023). "SFRP5 is a member of the secreted frizzled-related protein (SFRP) family and acts as a tumor suppressor and a secreted antagonist of the Wnt/β-catenin pathway." (PMID 37894456, 2023). "The SFRP5 low expression promotes EMT, tumor growth, invasion, tumor progression, and cisplatin resistance." (PMID 32850327, 2020). "To date, four SFRP family genes (SFRP1, SFRP2, SFRP4 and SFRP5) and two DKK family genes (DKK1 and DKK3) have been identified as targets of epigenetic silencing in human tumours." (PMID 18283316, 2008). "This is the first study to evaluate the concentrations of SFRP1, SFRP2, and SFRP5 in tumour and non-tumour (NT) samples from patients with primary NSCLC, including adenocarcinoma, squamous cell carcinoma, and large cell carcinoma." (PMID 37999144, 2023). "Tumor samples from 155 patients with stages IIIB to IV NSCLC who received EGFR-TKI therapy were analyzed for DNA methylation status of Wnt antagonist genes, including SFRP1, SFRP2, SFRP5, DKK3, WIF1, and APC, using methylation specific PCR (MSP) method." (PMID 23009178, 2012). "However, a closer look at the respective genes reveals that many of them (SFRP5, WISP3, DKK4, FRZB and JUP) are antagonists of the 'WNT-beta catenin' pathway, thus exerting a tumor suppressor role in normal conditions." (PMID 19327144, 2009). "However, the connections between the level of SFRP5 protein and tumour characteristics and prognosis for NSCLC patients has not been explored in the literature." (PMID 37999144, 2023). "However, the levels of SFRP1 and SFRP5 were not significantly different between tumour and NT samples (p > 0.05)." (PMID 37999144, 2023).
tumor (continued). "The expression among tumor stages varied significantly for SFRP2, SFRP3, and SFRP4, whereas the mRNA expressions of SFRP1 and SFRP5 were not markedly different." (PMID 34205081, 2021).
cancer (30 papers, 2008 to 2025). A tumor composed of atypical neoplastic, often pleomorphic cells that invade other tissues. "The aim of this study is to evaluate the relationship between the methylation and expression of APC, SFRP1, SFRP2, SFRP4, and SFRP5 genes involved in the Wnt signaling pathway and the risk of cancer development in IBD." (PMID 40521787, 2025). "This pathway is essential for cancer progression, and therapies designed to restore or replicate SFRP5 activity are currently being evaluated for their potential to treat cancer." (PMID 39202484, 2024). "SFRP5 (Secreted Frizzled Related Protein 5) gene codifies for one of the soluble Wnt signaling modulators that are involved in the regulation of cell proliferation and cancer progression." (PMID 37152062, 2023). "C-1 and C-2 cancer cells finally differentiated into the third cells state, which expressed SFRP5, a Wnt-signaling regulator." (PMID 34326696, 2021). "SFRP1, SFRP2, and SFRP5 were significantly correlated with the clinical cancer stage in GC patients." (PMID 34205081, 2021). "p16, TFPI2, the cadherins E-cadherin and CDH13, and the secreted frizzle-related proteins (SFRPs) SFRP1 and SFRP5 were desilenced in cancer cell lines." (PMID 23593653, 2013). "Other members of this family, such as SFRP2, SFRP4 and SFRP5, were also found to exert their roles in human cancers." (PMID 19586554, 2009). "Li found that SFRP5-Wnt11 signaling had profound effects on organogenesis and cancer." (PMID 35592316, 2022). "The secreted frizzled-related protein 5 gene (SFRP5) that antagonize the Wnt/β-catenin signaling is frequently inactivated by promoter methylation and oncogenic activation of the Wnt signaling pathway is common in many cancers." (PMID 31754130, 2019). "Neither are there any reports elucidating whether Wnt5a-SFRP5 interaction exists in human cancers, especially in ES, though SFRP5 has been shown to block macrophage activation through inhibition of Wnt5a/JNK signaling in fat tissues." (PMID 23075330, 2012). "Previous literature suggests that SFRP5 inhibits WNT5A, a β-catenin-independent WNT protein that plays a critical role in regulating cell signaling pathways involved in development and cancer progression." (PMID 40301374, 2025). "We examined DNA methylation levels of SFRP1, SFRP2, SFRP5, DKK2, DKK3, mir34b/c, RASSF1A, IGFBP7, CDKN2A, and MLH1 in cancerous glands and normal crypts isolated from cancer tissue and the surrounding normal mucosa." (PMID 28533824, 2017). "Compared to surrounding normal colonic crypts, the methylation levels of SFRP1, SFRP2, SFRP5, DKK2, DKK3, mir34b/c, and RASSF1A in MSS CRCs were significantly higher in cancer crypts." (PMID 28533824, 2017). "Previous studies have shown that promoters of most WNT antagonistic genes (sFRP1, sFRP2, sFRP3, sFRP5, DKKs, and WIF1) are methylated or epigenetically silenced in RCC, which results in uninhibited WNT signaling during cancer initiation or progression." (PMID 23094073, 2012). "In CRC, it is well established that SFRP5 transcript expression decreases due to promoter DNA hypermethylation, suggesting that the cancer cells are unlikely to be the origin of the heightened cSFRP5." (PMID 38872420, 2024). "We examined the DNA methylation levels of SFRP1, SFRP2, SFRP5, DKK2, DKK3, mir34b/c, RASSF1A, IGFBP7, CDKN2A, and MLH1 in normal colonic crypts isolated from regions that were adjacent to the cancer, as well as distal and proximal regions (left and right sides)." (PMID 28533824, 2017). "Sfrp5 belongs to the family of secreted frizzled related proteins (Sfrp), secreted inhibitors of Wingless-MMTV Integration Site (Wnt) signaling, which play an important role in cancer and development." (PMID 23638093, 2013). "At present, there are no FDA-approved cancer treatments that target PDE4B, PDE4D, or SFRP5." (PMID 39202484, 2024).
cardiovascular disease (10 papers, 2017 to 2025). "The SFRP5 rs780369540 polymorphism was significantly associated with disease risk, with the C allele showing lower cardiovascular disease prevalence." (PMID 41465371, 2025). "Studies found that SFRP5 was inversely proportional to cardiovascular disease risk factors, positively correlated with faster recovery after MI and seen to protect against re-perfusion injury." (PMID 36938497, 2022). "Multivariate analysis identified elevated Wnt5a, JAK, and decreased SFRP5 as independent predictors of cardiovascular disease (p < 0.05)." (PMID 41465371, 2025). "Previous studies have shown that SFRP5 can inhibit the occurrence and development of cardiovascular diseases." (PMID 40056066, 2025). "Numerous studies have supported the protective effect of sFRP5 against various cardiovascular diseases." (PMID 32429518, 2020). "SFRP5 has anti-inflammatory and metabolic regulatory effects, and it may play an important role in the occurrence and development of cardiovascular diseases." (PMID 35685732, 2022).
metabolic disorders (6 papers, 2015 to 2024). "SFRP5 has garnered attention as a promising therapeutic target for various conditions, including metabolic diseases." (PMID 38872420, 2024). "This ultimately demonstrates that the up-regulation of SFRP5 in obese and diabetic mice alleviates metabolic disorders and suppresses adipose tissue inflammation." (PMID 29789397, 2018). "Therefore, further research is needed to further investigate these mechanisms and gain a more comprehensive understanding of the role of SFRP5 in cardiovascular health and metabolic diseases." (PMID 37957661, 2023). "A number of hypotheses have been put forward suggesting that the SFRP5-Wnt5a modulatory axis in adipose tissues presents a novel promising target for controlling metabolic disorders." (PMID 29789397, 2018).
adenocarcinoma (3 papers, 2010 to 2023). A common cancer characterized by the presence of malignant glandular cells. "When we sub-grouped patients based on their demographic characteristics, we found that SFRP1 methylation significantly reduced DCR in patients older than 65 (P = 0.038) and sFRP5 methylation significantly reduced DCR in patients suffered adenocarcinoma (P = 0.042)." (PMID 23009178, 2012). "Therefore, further studies on a larger cohort are needed to confirm the role of SFRP5 in NSCLC, especially in adenocarcinoma." (PMID 37999144, 2023).